SIRT1 (sirtuin 1)
Diseases named in the same sentence as SIRT1 in open-access papers (continued):
Sharing a sentence is not in itself a finding about the gene and the disease.
liver fibrosis (continued). "This signaling pathway, especially SIRT1, might be a promising therapeutic target for liver fibrosis." (PMID 27387128, 2016). "Thus, we found that the levels of NAD + were significantly enhanced in fibrotic livers, further supporting the notion that sirtuin family members (SIRT1-7) may play important roles as crucial regulators of liver fibrosis and the deacetylation of RELA." (PMID 41322258, 2025). "SIRT1/2 may also target intracellular signaling pathways to regulate liver fibrosis." (PMID 38993557, 2024). "However, whether age‐dependent inhibition of hepatic SIRT1 is a driving force to promote liver fibrosis remains elusive." (PMID 36999514, 2023). "Additionally, we also provide the possible mechanisms GF which could mainly affect AMPK/SIRT1 pathway and/or Nrf2 signaling cascades on the liver fibrosis as well as chronic TAA exposure hepatic oxidative stress conditions." (PMID 34829709, 2021). "In liver fibrosis, SIRT1 may be transcriptionally repressed by HDAC4." (PMID 34899370, 2021). "In addition, a prior study also noted that SIRT1 exacerbates liver fibrosis in mice." (PMID 32324317, 2020). "Indeed, in HSC-specific SIRT1 knockout mice CCl4-induced liver fibrosis is exacerbated." (PMID 33086678, 2020). "Besides, liver fibrosis was exacerbated in mice with HSC-specific deletion of SIRT1." (PMID 33029279, 2020). "However, little research has focused on the role of SIRT1 in liver fibrosis." (PMID 31533364, 2019). "Thus, we hypothesized that SIRT1 may suppress ER stress in BDL-induced liver fibrosis, thereby affording a novel therapeutic target." (PMID 30455644, 2018). "Furthermore, SalA increased SIRT1 expression, suggesting that SalA may protect against BDL-induced liver fibrosis by up-regulating SIRT1." (PMID 30455644, 2018). "Thus, we concluded that PIAS4 might contribute to liver fibrosis by modulating SIRT1-depenent SMAD3 acetylation." (PMID 27323886, 2016). "Accordingly, our findings reveal the protective role BCP exerts through modulating AMPK/SIRT1/HIF1-α and thus protecting against liver fibrosis." (PMID 40943413, 2025). "This suggests a potential role of SIRT1-telomerase-HSC axis in the occurrence and development of liver fibrosis, warranting further investigation." (PMID 40052151, 2025). "In conclusion, SIRT1 occupies a crucial role in liver physiology and pathology, with its distinct functions in MASLD, ALD, HCC and liver fibrosis now increasingly well elucidated." (PMID 41281762, 2025). "Building on this mechanistic axis, the interplay between AMPK/SIRT-1/PGC-1α/PPAR-γ signaling and oxidative stress emerges as a central determinant in the progression and resolution of hepatic fibrosis." (PMID 41365955, 2025).
liver fibrosis (continued). "Age-related declines in SIRT1 activity trigger inflammatory pathways such as NOD-like receptor protein 3 (NLRP3) and Interleukin-1 beta (IL-1β), exacerbating liver fibrosis." (PMID 40052151, 2025). "This study demonstrated that daily oral treatment with sotagliflozin markedly upregulated antioxidant markers such as SIRT1 and Nrf2, attenuated TNF‐α, and reduced apoptotic and fibrogenic markers, thereby protecting against TAA‐induced liver fibrosis." (PMID 41498016, 2025). "Subsequently, in an in vitro model of liver fibrosis established by treating LX-2 cells (human HSCs) with TGF-β1, SIRT1 expression was markedly downregulated." (PMID 41281762, 2025). "The results of our study suggest that Remo has anti-inflammatory and antioxidant properties that protect against TAA-induced liver fibrosis by inhibiting the NF-κB pathway and activating the AMPK/SIRT1/Nrf2 pathway." (PMID 40552161, 2025). "At the 7.5 mg/kg dose, NIC significantly enhanced the expression of SIRT-1, AMPK, PGC1-α, PPARγ, and STAT3 by 2.43-, 2.56-, 3.14-, 1.76-, and 1.90-fold, respectively, compared to the TAA-induced liver fibrosis group, and reduced HIF-1α expression by 28.23%." (PMID 41365955, 2025). "The current study demonstrates the protective potential of Nicorandil (NIC) in alleviating liver fibrosis induced by TAA in rats, with a particular focus on the modulation of the AMPK/SIRT-1/HIF-1α signaling axis." (PMID 41365955, 2025). "To this aim, we used an experimental model of thioacetamide (TAA)-induced liver fibrosis, modulating the activity of AMP-activated protein kinase (AMPK)/Sirtuin-1 (SIRT-1) and inhibiting hypoxia-inducible factor 1-alpha (HIF-1α)." (PMID 40943413, 2025). "In contrast, sirtuin 1 (SIRT1), a NAD+-dependent deacetylase, has emerged as a crucial negative regulator of liver fibrosis." (PMID 40564221, 2025). "This study evaluates the efficacy of NIC in attenuating thioacetamide (TAA)-induced liver fibrosis in rats, focusing on the AMPK/SIRT-1/HIF-1α signaling pathway." (PMID 41365955, 2025). "Resveratrol has been shown to induce autophagy in immortalized mouse HSCs, dampening HSC activation through the SIRT1 and JNK signaling pathways, thus attenuating liver fibrosis." (PMID 39175576, 2024). "Resveratrol modulates autophagy and apoptosis via the SIRT1 and JNK signaling pathways, suppresses HSCs activation, and attenuates liver fibrosis in NAFLD." (PMID 39175576, 2024). "The variable expression of SIRT1 in hepatocytes, HSCs, and Kupffer cells, and its distinct roles in various liver diseases such as ALI, ALD, NAFLD, IRI, cholestatic injury, and liver fibrosis, underscore its complex function in hepatology." (PMID 38563003, 2024). "In an attempt of a better understanding of SIRT1/2 and their inhibitors, we evaluated the effect of Tenovin-1, on HFD-induced Hepatic Fibrosis in ZDF rats and an FFA-treated SCC model." (PMID 38993557, 2024). "A histone deacetylase enzyme, Sirtuin 1 (SIRT1), can deacetylate EZH2 to decrease its stability and lead to the de-repression of PPARγ in liver fibrosis." (PMID 37476157, 2023). "Deletion of SIRT1 in hepatocytes enhances NLRP3 signaling and triggers HSC activation and liver fibrosis in young mice in response to liver injury." (PMID 36999514, 2023). "We didn't observe the differences on SIRT1 mRNA level in RNA sequencing data, which prompted us to explore the relationship between FAT10 and SIRT1 in liver fibrosis." (PMID 37057207, 2023). "Mechanistically, deletion of SIRT1 in hepatocytes resulted in NLRP3 and IL‐1β induction, pro‐inflammatory response, and severe liver fibrosis in young mice, mimicking the ability of aging to impair the resolution of established fibrosis." (PMID 36999514, 2023). "In the present study, DPx induced upregulations of SIRT1 and SIRT3 by DPx showed amelioration of TAA-induced liver fibrosis." (PMID 37324954, 2023).
liver fibrosis (continued). "The data of SEM and HE staining showed that the overexpression of SIRT1 with the adenovirus vector reversed CCl4-induced LSEC defenestration on the 6th day and alleviated the first stage of liver fibrosis on the 28th day." (PMID 36497176, 2022). "We further observed that SIRT1 target oxidative stress-related proteins such as NOX2 and p47phox were significantly normalized by GF 200 against TAA-injected hepatic fibrosis (p < 0.05 or 0.01)." (PMID 34829709, 2021). "On the other hand, SIRT1 can participate in fibrosis by regulating the transforming growth factor β (TGF-β) signaling pathway, which is very important in liver fibrosis." (PMID 30995792, 2019). "In this study, we discovered that HSF1 regulates ER stress in liver fibrosis, and SalA regulates HSF1 by up-regulating SIRT1." (PMID 30455644, 2018). "We found that the increased expression of SIRT1 leads to the deacetylation of HSF1 and up-regulation of heat shock proteins, which can relive liver fibrosis through inhibition of ER stress." (PMID 30455644, 2018). "In addition, MALAT1 may mediate SIRT1 expression and function in cases of liver fibrosis." (PMID 28835896, 2017). "In conclusion, we present evidence that PIAS-mediated transcriptional repression of SIRT1 contributes to HSC activation and liver fibrosis in the context of NASH pathogenesis." (PMID 27323886, 2016). "Taken together, our data suggest SIRT1 trans-repression by PIAS4 plays an important role in HSC activation and liver fibrosis." (PMID 27323886, 2016). "PIAS4 promotes HSC activation and liver fibrosis by stimulating SMAD3 acetylation and target binding in a SIRT1-dependent manner." (PMID 27323886, 2016). "Moreover, resveratrol (RSV) has been shown to counteract arsenic-induced hepatocyte senescence by restoring SIRT1’s inhibitory effect on p16, thus suppressing SASP-related protein release, reducing fibrotic phenotypes and mitigating liver fibrosis." (PMID 40052151, 2025). "Therefore, the current study aims to investigate the therapeutic potential of NIC in TAA-induced liver fibrosis in rats, focusing on its ability to regulate the AMPK/SIRT-1/HIF-1α axis and promote liver regeneration." (PMID 41365955, 2025). "SIRT1/Nrf2 and PI3K/AKT signaling pathways are two of the key network pathways in which sotagliflozin exhibits additional therapeutic benefits when used to modify the pathophysiology of liver fibrosis." (PMID 41498016, 2025). "In the present study, we hypothesized that a SIRT1/2 inhibitor, due to its SIRT1/2 deacetylase inhibition activity, can attenuate HSC activation and HFD-induced hepatic fibrosis in diabetic rats." (PMID 38993557, 2024). "Our findings demonstrate an improved understanding towards the role of SIRT1/2 inhibition in liver fibrosis with or without diabetes and validates Tenovin-1 as a potential option for its treatment." (PMID 38993557, 2024). "In this manuscript, we summarized the role of SIRT1 in acute liver injury (ALI), alcoholic liver disease (ALD), nonalcoholic fatty liver disease (NAFLD), ischemia-reperfusion injury (IRI), cholestatic injury, and liver fibrosis." (PMID 38563003, 2024). "SIRT1 protects against APAP-induced liver injury, liver fibrosis and other hepatic diseases." (PMID 37107244, 2023). "The concept that SIRT1 serves as a negative regulator of NLRP3 in hepatocytes is strengthened by the fact that deletion of SIRT1 in hepatocytes leads to NLRP3+ cell elevation and severe liver fibrosis in young mice, mimicking the effect of aging on NLRP3 signaling." (PMID 36999514, 2023). "Sirt1-mediated deacetylation of the intracellular domain of Notch (NICD) led to degradation of NICD, thereby inhibiting Notch signalling pathway to alleviate liver fibrosis." (PMID 35582617, 2022). "In summary, SIRT1 drives the nucleophagic degradation of progerin mediated by the deacetylation of nuclear LC3 and improves the depletion of Lamin B1 and Cav-1, leading to the maintenance of LSEC fenestrae and the relief of liver fibrosis." (PMID 36497176, 2022).
liver fibrosis (continued). "This led us to test the hypothesis that SIRT1-regulated progerin degradation, which was potentially mediated by nucleophagy, could protect against LSEC defenestration and liver fibrosis." (PMID 36497176, 2022). "Intriguingly, SIRT1 gene transfer to CCl4-induced liver fibrosis rat models could attenuate LSEC defenestration and liver fibrosis, despite enhanced autophagy being induced by overexpressing SIRT1." (PMID 36497176, 2022). "Consistently, ethanol fed liver-specific deletion of SIRT1 (Sirt1LKO) promotes ethanol-mediated liver fibrosis in the livers, as indicated by increased levels of α-SMA and early markers of hepatic fibrosis such as collagen I, tissue inhibitor of metalloproteinase 1 (Timp-1), or TGF-β115." (PMID 33162823, 2020). "We hypothesize that EX-527, a selective SIRT1 inhibitor, can inhibit the progression of high-fat diet (HFD)-induced hepatic fibrosis." (PMID 32365537, 2020). "SIRT1 has long been identified as the target protein of miR-34a, although there have been no reports linking upregulation of miR-34a with SIRT1 in liver fibrosis." (PMID 27387128, 2016). "AMPK, Sirt1, and eNOS are key regulators of hepatic energy and lipid metabolism, as well as inflammation, oxidative stress, and cell proliferation, the key factors for progression of simple NAFLD to NASH and liver fibrosis." (PMID 28042486, 2016). "We show here that lentivirus mediated PIAS4 knockdown in MCD-fed mice alleviates liver fibrosis, which could be explained by PIAS4 mediated SIRT1 trans-repression in HSCs." (PMID 27323886, 2016). "However, WFA had no obvious effect on SIRT1 expression but notably increased the SIRT3 expression, suggesting that SIRT3 but not SIRT1 contributed to the preventive effect of WFA on liver fibrosis." (PMID 33029279, 2020). "However, the exact regulation of SIRT1 expression levels in liver fibrosis has not been illuminated." (PMID 31533364, 2019). "The objective of this study was to investigate the effect of SIRT1-mediated inhibition of ER stress in bile duct ligation (BDL)-induced liver fibrosis, and to explore the effect of salvianolic acid A (SalA) on BDL-induced liver fibrosis through SIRT1/heat shock factor 1 (HSF1) signaling." (PMID 30455644, 2018). "On the other hand, SIRT1 that is an epigenetic regulator well known to NAD+-dependent histone deacetylase is deeply implicated in liver diseases by modulations of redox status, inflammation, and cell death, respectively; however, its roles in liver fibrosis is not clearly studied yet." (PMID 34829709, 2021). "Tenovin-1 is a potent inhibitor of SIRT1/2 deacetylating activity and an increase in SIRTs could not be a possible outcome as Tenovin-1's response to hepatic injury, the protective action of Tenovin-1 against hepatic fibrosis can be attributed to its reduction in SIRT1/2 activity." (PMID 38993557, 2024). "Unlike SIRT1, SIRT2 may promote liver fibrosis because inhibition of its activity results in a decreased activity of other fibrosis-related proteins, such as alpha-SMA, COL1A1, MMP2, TIMP-1, and TIMP-2." (PMID 34899370, 2021). "Interestingly, treatment with celastrol increased SIRT3 but not SIRT1 mRNA expression, suggesting that SIRT3 participated in the attenuation effect of celastrol on liver fibrosis." (PMID 31742890, 2020).
heart failure (87 papers, 2011 to 2026). Inability of the heart to pump blood at an adequate rate to meet tissue metabolic requirements. "The development of heart failure is closely linked to mitochondrial dysfunction, with SIRT1 modulating the maladaptive metabolic response of cardiomyocytes under conditions of pressure overload." (PMID 41009597, 2025). "This study investigates the interaction between SIRT1 and H2S in heart failure and the underlying mechanisms." (PMID 36757027, 2023). "Insufficient autophagy during heart failure is associated with impaired SIRT1/PGC-1α and AMPK signaling, as well as the activation of the Akt/mTOR pathway." (PMID 37754811, 2023). "A loss of SIRT1 activity contributed to NFκB-p65 activation and chronic cardiac pathology and heart failure in CCM." (PMID 27764247, 2016). "We investigated the mechanisms underlying resveratrol-mediated protection against heart failure in diabetic mice, with a focus on the role of sirtuin 1 (SIRT1) in regulating autophagic flux." (PMID 24889822, 2014). "The expression of Sirt1 and other (associated) downstream molecules in human cardiomyocytes from patients with advanced heart failure was examined." (PMID 24913149, 2014). "This is a cross-sectional study designed to investigate the expression of Sirt1 and its associated molecules in the left atrium from the end-stage heart failure patients, and compared those from even younger donors." (PMID 24913149, 2014). "Since derangement of these physiological processes underlies the development/progression of heart failure, pharmacologic activation of SIRT1 and/or SIRT3 potentially ameliorates the disease." (PMID 22622703, 2012). "Sirt1 activates or inactivates apoptosis-associated proteins through deacetylation, thereby inhibiting apoptosis to ameliorate myocardial remodeling and delay the progression of heart failure." (PMID 36843938, 2023). "It is particularly interesting that E2 could promote SIRT1 expression in stress conditions because clinical association studies revealed an association between E2 and heart failure; and overexpression of SIRT1 could block cell hypertrophy and apoptosis." (PMID 25614777, 2014). "These Sirt1 agonists may prevent changes associated with cardiac aging, and targeting Sirt1 may become a promising modality to protect the heart from aging or heart failure." (PMID 24913149, 2014). "In a rat model of heart failure, Sirt1 expression was reduced, while NF-κB p65 and miR-155 were found to be upregulated, and BDNF was downregulated, which contributed to cardiac dysfunction and increased apoptosis." (PMID 41226851, 2025). "The aim of this study was to investigate the mechanisms between heart failure‐induced renal fibrosis and the SIRT1‐FoxO1‐FoxO3‐autophagy pathway within the framework of cardiorenal syndrome." (PMID 40197776, 2025). "Sirt1 has a protective function in heart failure by modulating the NF-κB p65/miR-155/BDNF signaling pathway." (PMID 41226851, 2025). "In heart failure models, SIRT1-mediated ferroptosis plays a crucial role in the pathogenesis, with AKG improving cardiac dysfunction through mitochondrial autophagy and ferroptosis inhibition mediated by the NAD + -SIRT1 signaling pathway." (PMID 40109363, 2025). "Sirt1 knockout C57BL/6J mouse in aortic coarctation heart failure model.Using isoproterenol to establish HiPSC cell model." (PMID 41394800, 2025). "Wenxin Keli enhances energy metabolism and improves Cx43 function in post-MI heart failure rats by activating the AMPK/SIRT1/PGC-1α signaling pathway." (PMID 40994651, 2025). "SIRT1 also increases the deacetylation of FOXO3a, which in turn prevents apoptosis and ameliorates heart failure." (PMID 40710369, 2025).